EPCAM (epithelial cell adhesion molecule)
Diseases named in the same sentence as EPCAM in open-access papers (continued):
Sharing a sentence is not in itself a finding about the gene and the disease.
tumor (continued). "Herein, the fluorescence imaging of tdEVs with αCK-PE staining and their capture by αEpCAM ferrofluid, which are both epithelial specific markers, with CK being expressed in the interior of epithelial cells and EpCAM on their surface, confirm their epithelial/tumor origin." (PMID 30384500, 2018). "Overall, as a response to chemotherapy, the ratio of PC-3-EpCAM-KD tumour volumes decreased faster in response to RT compared to the sham irradiation (P < 0.05), suggesting that the KD of EpCAM can also increase the radiosensitivity of CaP tumours in orthotopic mouse model." (PMID 30419852, 2018). "In order to capitalise on the ability of antibodies to specifically target tumour cells, as well as to produce an efficacious therapeutic, the next step in developing EpCAM as a target for enhanced cytotoxicity has been to combine antibodies with cytotoxic drugs." (PMID 29329202, 2018). "Epithelial cell adhesion molecule (EpCAM) is a glycoprotein on the surface of epithelial cells that is essential for intestinal epithelial integrity and expressed at high levels in many epithelial derived cancers and circulating tumor cells." (PMID 30304739, 2018). "Overall, as its response to chemotherapy, the ratio of PC-3-EpCAM-KD tumour volumes decreased faster in response to RT compared to the sham irradiation (P < 0.05), suggesting that the KD of EpCAM can increase the radiosensitivity of CaP tumours in s.c. mouse model." (PMID 30419852, 2018). "Whether EpCAM acts as a tumour suppressive gene or as an oncogene might depend on the cell type and microenvironment." (PMID 29305578, 2018). "To identify tumor‐suppressive miRNAs repressed by DNA hypermethylation in highly tumorigenic GC, we isolated EpCAM+/CD44+ GC cells from primary GC tumor tissues and performed methyl‐CpG‐binding domain (MBD) sequencing (MBD‐seq) and miRNA sequencing (miRNA‐seq)." (PMID 29862663, 2018). "Since EMT CTCs have also been correlated with disease progression and chemotherapy resistance; enrichment systems that allow simultaneous investigation of both EpCAM+ and EpCAM− CTCs are being employed in order to obtain more complete information about the role of EpCAM in tumor progression." (PMID 30200242, 2018). "Whereas, tumour associated immune cells (TAMS), tumour associated fibroblasts (e.g., FAP, α-SMA, FGFRs, tenascin-C and thrombospondin-1) and tumour initiating stem cells (e.g., CD133, EpCAM and aldehyde dehydrogenases), have been utilised to allow for NPPSs drug targeting within a TME." (PMID 30322132, 2018). "Otherwise, higher numbers of CTCs could be detected using alternative methods, suggesting that a mixture of EPCAM+ and EPCAM- tumour cells circulate in the blood." (PMID 30450210, 2018). "Given that there are few markers to utilize for targeted therapeutics for triple negative breast cancer and that EpCAM is present in close to 64% of these patients’ tumours, it may represent a viable target for targeted medical imaging." (PMID 30586898, 2018). "A similar proportion of CTCs and tumor cells expressed EPCAM, at 50% and 53%, respectively." (PMID 29568081, 2018). "Notably, subcutaneous tumor tissues obtained from Milano hcc-2 contained similar epithelial cell-shaped EpCAM+ cells and mesenchymal cell-shaped CD90+ cells." (PMID 28900199, 2017). "Notably, the majority of ALDH+ cells were also EpCAM+, which has the same capability to form sphere-like colonies from xenograft tumours." (PMID 28440295, 2017). "Although EpCAM has great value for the capturing of CTCs from the blood of patients, drawbacks relate to its long assumed continuous expression in all phases of tumor progression, including circulating tumor cells." (PMID 27683128, 2017). "As expected from the proteomic data, EPCAM demonstrated the greatest specificity for tumor cells." (PMID 28336725, 2017).
tumor (continued). "Correlating with these results in vitro, the expression of the tumor-initiating markers EpCAM, CD90, and Myc was significantly increased in the Ath+HF group compared with the basal diet group and their expression was significantly repressed in the Ath+HF+BCAA group." (PMID 28212548, 2017). "A total of two studies reported EpCAM overexpression in groups with tumour sizes >5 cm and ≤5 cm." (PMID 28403178, 2017). "Finally, levels of tumour cell cytotoxicity achieved were compared using EpCAM BiTE to activate purified CD4+ and CD8+ subsets." (PMID 28634161, 2017). "We found that in most PDXs tumor initiating capacity was enriched in the CD49f+/EpCAM+ population." (PMID 29162812, 2017). "Multiple novel tumor-specific candidates are proposed and EPCAM was verified by IHC." (PMID 28336725, 2017). "In contrast, CKs and EpCAM were detected at similar levels in the primary tumor tissue." (PMID 29290959, 2017). "Furthermore, in contrast to normal mammary epithelial cells were the repopulating ability is enriched in the CD49f+/EpCAMmed-low population, we find that in TNBC samples tumor initiating capacity is highest in CD49f+/EpCAM+ population." (PMID 29162812, 2017). "Tumor cells were identified as EpCAM- and/or pan-keratin-positive (green) and CD45-negative (red)." (PMID 28842574, 2017). "All tumor sections showed strong membranous immunostaining for EpCAM." (PMID 28176469, 2017). "BiTEs have been designed to target a variety of tumor antigens such as CD19, EphA2 receptor tyrosine kinase, EpCAM, EGFR, melanoma-associated chondroitin sulfate proteoglycan, and CD33, among others, and have shown therapeutic efficacy in mouse tumor models." (PMID 28938530, 2017). "The isolated tumor cells were stained for EpCAM and keratins." (PMID 28842574, 2017). "We moved on to test in vivo tumor killing effects of the T cells stably expressing anti-EpCAM CAR." (PMID 28088790, 2017). "Therefore, the aim of the present study was to compare genomic changes in CD133+ cells versus differentiated (CD133−/EpCAM+) enriched tumour cells from intraoperative human tumour biopsies." (PMID 28347289, 2017). "Distinct differentiation states of human mammary epithelial cells grown in cell cultures lead to different tumor subtypes in mouse xenografts, e.g., EpCAM+ cells form epithelial tumors with variable ER-positivity, while CD10+ cells are precursors of metaplastic carcinoma." (PMID 29276709, 2017). "Notably, circulating tumor cells express high levels of epithelial cell adhesion molecule (EpCAM), also known as CD147." (PMID 28279189, 2017). "In addition, the blood-based diagnosis of OC via three exosomal protein markers for tumor (CA125, EpCAM, and CD24) showed significant diagnostic power in that tumor testing with a drop of blood was possible." (PMID 28506269, 2017). "However, an important and well-known limitation of the CellSearch platform is that enrichment is based on tumor cells expressing epithelial cell adhesion molecules (EpCAM)." (PMID 29190932, 2017). "Besides, a novel recombinant antibody E3Bi enhanced the specific cytotoxicity of activated T cell (ATC) in tumor cell lines with high EpCAM expression and significantly inhibited tumor growth in mice model." (PMID 28931402, 2017). "Furthermore, after 4 weeks, EpCAM positive circulating tumor cells were found almost exclusively in mice injected with RHAMM+ cells." (PMID 29050306, 2017). "One of the scFvs binds to EpCAM expressed on tumor cells, and the other binds to CD3 on T cells." (PMID 28931402, 2017). "Results suggested fibroblast activation protein alpha and epithelial cell adhesion molecule circulating tumor cells are distinct subpopulations and the use of these in concert can provide information needed to navigate through cancer disease management challenges." (PMID 29657983, 2017). "However, it is nowadays clear that EpCAM is subject to dynamic changes in expression throughout tumor progression, including changes related to mesenchymal transitions." (PMID 27683128, 2017).
tumor (continued). "Moreover, blockage of β‐catenin by RNA‐interference strategy significantly abolished the capacity of tumor spheroid formation in those ZFX‐expressed EpCAM+ HCC cells." (PMID 28156061, 2017). "More importantly, MSC displayed differential homing potential toward tumor cells associated with higher oncogenicity and not the cleaved extracellular domain of EpCAM or HCC cells expressing low fraction of EpICD." (PMID 28903370, 2017). "The enrichment of miR-429 in HCC cells, especially in epithelial cell adhesion molecule (EPCAM)+ -tumor initiating cells (T-ICs) could lead to shedding of miR-429-harboring exosomes, thus facilitating tumor formation." (PMID 27713136, 2017). "Gene expression in tumor EPCAM+CD44+CD49f+ cells further segregated intratumoral from lymph node EPCAM+CD44+CD49f+ cells with 381 genes differentially expressed, including upregulation of genes involved in immune responses and cell adhesion (Gene Ontology) in lymph node EPCAM+CD44+CD49f+ cells." (PMID 28487492, 2017). "Median EpCAM expression (TIS) in primary tumor was 6.0 (inter quartile range 2.3–11.0)." (PMID 28820475, 2017). "We then assessed whether the EpCAM BiTE would kill a range of tumour cells, and whether the level of EpCAM BiTE‐mediated cytotoxicity observed was dependent on the density of EpCAM expression." (PMID 28634161, 2017). "In addition, a limiting dilution assay showed that ALDH+/EpCAM+ cells had a much greater ability to reform secondary tumours, as compared with ALDH-/EpCAM+ cells." (PMID 28440295, 2017). "In this case, we targeted them to kill EpCAM‐positive tumour cells." (PMID 28634161, 2017). "By combining the three most suitable markers for the ductal (E-cadherin, EMA and Her2/neu) and lobular (EMA, Her2/neu and EpCAM) subtypes, 100% tumor cell detection was accomplished in 53 out of 58 ductal ovarian metastases and in 7 out of 10 lobular ovarian metastases." (PMID 28327103, 2017). "Furthermore, our results obtained using quantitative fluorescence analyses show that the level of EpCAM expression of MCF-7 tumor cells is similar before and after their live cell enrichment by ISET®." (PMID 28060956, 2017). "There is no clear explanation for this observation; however, we cannot exclude that the expression of TTF-1 and CD56 molecules in CTCs are not related with the invasive potential or the aggressivity of tumor cells in contrast with the more epithelial EpCAM+/CK+ CTCs detected by CS." (PMID 28349943, 2017). "Further, the platform presents the ability for users to assess different areas of the FNAB tumor sample and with coordinating protein markers such as EpCAM and CD44 to know which cells are undergoing cell death or continued viability and evasion of drug response." (PMID 28085924, 2017). "Enrichment for gene sets related to lipid metabolism and the immune system in the EPCAM+CD44+CD49f+ cells compared to the bulk tumor population, which included tumor-infiltrating and stromal cells, may represent pathways unique to EPCAM+CD44+CD49f+ cells." (PMID 28487492, 2017). "A trend of increase was found in EVs expressing of the tumor marker EpCAM in the neo-adjuvant patients before chemotherapy, which may indicate tumor existence in this patient group." (PMID 28968987, 2017). "All evaluated tumors in our study were invasive, which could explain the differences of EpCAM expression in the primary tumor as well." (PMID 28820475, 2017). "Another important issue when using antibodies targeting EpCAM is that the expression of this protein may vary in tumor cells during disease progression, and expression can be down-regulated as a consequence of epithelial-to-mesenchymal transition (EMT)." (PMID 27316334, 2016). "Epithelial cell adhesion molecule (EpCAM) was one of component of the tumor microenvironment." (PMID 26883295, 2016).
tumor (continued). "We observed that H-2Kd/EpCAM double positive murine cells are present in our PDX tumor samples and could reflect species cross-reactivity of the primary antibody, which would be particularly problematic in the case of tumors with low EpCAM expression." (PMID 27611664, 2016). "Thus, we used immunocytochemistry with cancer-specific markers in effusions such as TTF-1 or the epithelial marker EpCAM combined with the mesothelial marker calretinin to better quantify tumor cells across passages." (PMID 27548442, 2016). "Aptamer-siRNA chimeras have already been used effectively in xenografted mice to target particular oncogenes for knockdown only in cancer cells (using an aptamer designed for EpCAM, a cell surface antigen that is highly expressed in most epithelial cancers) in order to suppress tumor growth." (PMID 27112956, 2016). "EpCAM has a dual role as a tumour suppressor gene or as an oncogene, and it has been proposed that epigenetic dysregulation could underlyieEpCAM expression." (PMID 27711186, 2016). "However, EpCAM+CD147+taMPs were greatly mirroring tumour volume with a significant dependence (r = 0.73)." (PMID 27127176, 2016). "In IHC, multivariate analyses demonstrated that Lgr5, CD133 and EpCAM were independently related to old age, CD133 and Sox2 were independently associated with well or moderate differentiation, while Oct4, CD133 and EpCAM were independently related to tumor progression." (PMID 27557490, 2016). "Furthermore, SSX2 was specifically enriched in the CD45−/EpCAM+/CD63+ subpopulation, which marks prostate-specific circulating tumor cells while differentiating from erythroid progenitor CD45−/EpCAM+ cells." (PMID 27276714, 2016). "In addition, between PDX-1/CD132+-1.1 and PDX-1/CD132+-1.2 xenografts, we observed a decreased frequency of CD133+ CSCs while an increasing fraction of tumor cells expressed EpCAM." (PMID 26551931, 2016). "The biological methods mainly rely on antigen-antibody binding, and antibodies against tumor specific biomarkers including epithelial cell adhesion molecule (EpCAM), human epidermal growth factor receptor 2 (Her2), and prostate-specific antigen (PSA) are usually used in CTCs purification." (PMID 27403030, 2016). "Furthermore, epithelial cell adhesion molecule (Ep-CAM) has been confirmed to be involved in tumor budding." (PMID 27843459, 2016). "Therefore, we suggest that EPCAM IHC should be performed on primary CRC tissues before the EPCAM-based detection of circulating tumor cells is applied in patients with CRC." (PMID 26528695, 2016). "Additionally, EpCAM is a prominent cell surface antigen for detection of circulating tumour cells (CTCs) and part of the commercially available CellSearchTM system (Veridex LLC, Raritan, NJ, USA)." (PMID 27127176, 2016). "The use of an antibody with low or intermediate EpCAM affinity for EpCAM might promote a more homogenous distribution and avoid adverse effects at the cost of a lower total tumour uptake." (PMID 27842504, 2016). "During this transition the expressions of epithelial markers such as EpCAM and cytokeratin is assumed to be downregulated and circulating tumor cells may become undetectable." (PMID 27340862, 2016). "In addition, nine corresponding primary tumours and brain metastases were analysed for EpCAM expression." (PMID 27302574, 2016). "Especially the observation of a humoral anti-EpCAM response confirms the potential of the trifunctional antibody to induce a polyclonal anti-tumor response against tumor-associated antigens which are not targeted by the trifunctional antibody itself." (PMID 27387446, 2016). "The EpCAM membranous molecule is a tumor marker widely used to capture circulatory tumor cells." (PMID 27528032, 2016). "Although the anti-EpCAM/800CW conjugate performed well in various tumour types, this probe could still be optimized." (PMID 27842504, 2016).
tumor (continued). "However, in a detailed analysis, we found that the presence of EPCAM-loss foci completely corresponded with the presence of poorly differentiated tumor clusters in metastatic lesions of EPCAM-PL CRCs." (PMID 26528695, 2016). "Unbiased efficient capture of heterogeneous populations of CTCs regardless their EpCAM expression status is important, as EpCAM expression in tumor cells varies between patient to patient and within a patient over time as it is rapidly down-regulated during EMT." (PMID 27501846, 2016). "Together, it is clear that some CTCs may experience phenotypic changes during tumor evolution and that the expression of EpCAM may be transient, so EpCAM expression based methods may potentially miss a substantial subset of CTCs." (PMID 27501846, 2016). "Importantly, downregulation of β-catenin and EpCAM proteins was clearly observed in tumor xenografts of WM130-treated groups." (PMID 27783993, 2016). "To determine whether decreased EpCAM in HCC cells would affect the tumor growth in vivo, we used Hep3B cells which were sensitive to doxorubicin for the xenograft study." (PMID 26984381, 2016). "To exclude non-tumour cells, we sorted for cells that were EPCAM+ carcinoma cells." (PMID 27325363, 2016). "However, EpCAM is only partially expressed in certain types of cancers, leading to inefficient capture and the escape of CTCs from EpCAM-based detection, which is further exacerbated by the fact of tumor heterogeneity." (PMID 27494883, 2016). "Any metastasizing tumor cells derived from EPCAM-CL or EPCAM-PL CRC may show loss or downregulation of EPCAM expression, and in these cases, the circulating tumor cells cannot be detected although they are actually present." (PMID 26528695, 2016). "Interestingly, the analysis of telomere length among different cells according to EpCAM expression status has shown that longer telomeres were present in HCC tumor cells that expressed EpCAM, compared to tumor cells that were EpCAM-negative." (PMID 26999107, 2016). "EpCAM has itself become a controversial marker for epithelial tumor cells." (PMID 27611664, 2016). "Among the 25 pre-operative biopsy tissues, partial EPCAM-loss foci were observed in 9 of 24 EPCAM-PL cases (38%), and complete negativity of EPCAM expression was observed in one case that had been originally determined to be an EPCAM-CL tumor with EPCAM germline deletion." (PMID 26528695, 2016). "On the contrary, EpCAM positive tumor cells were enriched in miliary ascites (FDR=0.041)." (PMID 27665539, 2016). "Compared with EpCAM− cells, only EpCAM+ cells could effectively initiate the development of invasive tumors in the case of xenografted tumor in NOD/SCID mice even after serial transplantation." (PMID 27610139, 2016). "We speculate that CD147+EpCAM− MPs were shed from fibroblast, T-cells, stroma cells, epithelial cells during tumour resection indicating tissue remodelling, migration and cancer cell invasion in which EMMPRIN/CD147 might play role as suggested by others." (PMID 27127176, 2016). "Further investigations based on the isolation of viable EpCAM + p75NTR+ CTCs may shed light on the molecular and biological roles of these cells in tumor metastasis in ESCC as well." (PMID 26897248, 2016). "However, as most of the systems for the detection of circulating tumor cells were based on the epithelial cell surface marker EpCAM, which is downregulated within the EMT process." (PMID 27529216, 2016). "However, the exact mechanisms by which EpCAM cleavage and EpEX signaling lead to tumor malignancy are yet to be established." (PMID 26317650, 2015). "Other studies have shown that the activated Wnt/β-catenin pathway regulates EpCAM expression, indicating that EpCAM may be involved in the β-catenin-mediated self-renewal ability of tumor cells." (PMID 26317650, 2015). "It is known that EpCAM is frequently expressed throughout different tumor entities." (PMID 26695635, 2015).